TCAF2 (TRPM8 channel associated factor 2)
Description:
[Isoform 2]: Negatively regulates the plasma membrane cation channel TRPM8 activity. Involved in the recruitment of TRPM8 to the cell surface. Promotes prostate cancer cell migration stimulation in a TRPM8-dependent manner.
Synonyms: FAM115C; FAM139A; FLJ40722; GATD9B; GATD9
Tractability: Antibody: UniProt places it where antibodies can reach, with high confidence; its Gene Ontology location is reachable by antibodies, with high confidence; the Human Protein Atlas places it where antibodies can reach.
Gene: Protein-coding gene on chromosome 7 (143,620,952 to 143,730,410, forward strand). Ensembl gene ENSG00000170379.
Subcellular location: Cell membrane (Isoform 2)
Subcellular location (Human Protein Atlas): Cell Junctions; Plasma membrane
Gene Ontology:
Molecular function: protein binding; transmembrane transporter binding
Biological process: negative regulation of anion channel activity; positive regulation of cell migration; positive regulation of protein targeting to membrane; regulation of monoatomic anion transmembrane transport
Cellular component: cell junction; plasma membrane
Genetic constraint (gnomAD): Loss-of-function variants: 5 observed, 11.12 expected, observed/expected ratio (o/e) 0.45, 90% interval 0.23 to 0.95. The synonymous counts are far from expectation, so gnomAD's model fits this gene poorly and the ratio says little. Missense variants: 100 observed, 183.44 expected, observed/expected ratio (o/e) 0.55, 90% interval 0.46 to 0.64. Synonymous variants: 32 observed, 70.03 expected, observed/expected ratio (o/e) 0.46, 90% interval 0.34 to 0.61.
Homologues: Orthologues: macaque TCAF2 (96% identical), dog TCAF2 (80% identical), chimpanzee TCAF2 (77% identical), mouse Tcaf2 (75% identical), rat Tcaf2c (74% identical), tropical clawed frog tcaf1 (46% identical), zebrafish zgc:162193 (41% identical), zebrafish si:ch211-210b2.4 (40% identical), zebrafish si:ch211-210b2.3 (40% identical), zebrafish si:ch211-210b2.2 (40% identical). Paralogues in human: TCAF2C (77% identical), TCAF1 (65% identical).
Diseases named in the same sentence as TCAF2 in open-access papers:
TCAF2 is named in the same sentence as 12 diseases in open-access papers, as found by Europe PMC text mining. Sharing a sentence is not in itself a finding about the gene and the disease. The quoted sentences say what the papers report.
prostate carcinoma (6 papers, 2020 to 2024). A carcinoma that arises from epithelial cells of the prostate gland. "Prior research on prostate cancer has unearthed parallel findings, where TCAF2’s interaction with TRPM8 facilitates its cell surface transport and suppresses its ion channel activity, effectively enhancing the migration of prostate cancer cells in vitro." (PMID 39062591, 2024). "Earlier studies reported that TCAF2, as a chaperone of TMPR8, is implicated in invasiveness/migration for both pancreatic and prostate cancer." (PMID 38019450, 2024). "The recruitment of TRPM8 to the cellular membrane and the facilitation of migration in prostate cancer cells is attributed to the actions of TCAF2, which operates in a TRPM8-dependent manner." (PMID 38019450, 2024). "TCAF2 promotes cell migration in prostate cancer by recruiting TRPM8 to the cell membrane, whereas TCAF1 reduces the speed and migration of these cells." (PMID 36012311, 2022).
pancreatic cancer (4 papers, 2020 to 2024). "Studies have shown that TCAF2 is also involved in the malignant biological behavior of pancreatic cancer cells, affecting the prognosis of pancreatic cancer patients." (PMID 38019450, 2024). "First, using the GEPIA web platform as a bioinformatic tool, we explored the transcriptional levels of TRPV6, TRPA1, TRPM8, TCAF1, and TCAF2 in pancreatic cancer (n = 179) and normal pancreatic tissues (n = 171)." (PMID 36012311, 2022). "First, we queried GEPIA to explore the relationship between the TRPV6, TRPA1, TRPM8, TCAF1, and TCAF2 mRNA expressions and sub-stages in pancreatic cancer samples, compared to the control (normal subjects)." (PMID 36012311, 2022). "Consistent with the GEPIA results, the expression levels of TRPA1, TRPM8, TCAF1, and TCAF2 were significantly higher in pancreatic cancer tissue (p < 0.001), and TRPV6 expression was significantly lower in pancreatic cancer tissue compared to normal tissues (p < 0.001)." (PMID 36012311, 2022). "Next, we used UCSC Xena to explore the expression levels of TRPV6, TRPA1, TCAF1, TCAF2, and TRPM8 in pancreatic cancer (n = 178) and in normal pancreatic tissue (n = 167)." (PMID 36012311, 2022).
colorectal cancer (3 papers, 2023 to 2024). A primary or metastatic malignant neoplasm that affects the colon or rectum. "The latest research reports that TCAF2 can facilitate distant metastasis in colorectal cancer, and TCAF2 also involves glioma, which is associated with the immune microenvironment of glioma and promotes malignant progression." (PMID 38019450, 2024). "Recent research reports that TCAF2 in peritumoral stromal cells promotes liver metastasis in colorectal cancer by inhibiting the cold-sensing TRPM8 channel." (PMID 38019450, 2024).
glioma (2 papers, 2024). A benign or malignant brain and spinal cord tumor that arises from glial cells (astrocytes, oligodendrocytes, ependymal cells). "After classifying gliomas in the TCGA database according to the WHO 5th edition classification of central nervous system tumors, it was observed that the expression of TCAF2 increased with tumor grade in the IDH mutation group." (PMID 38019450, 2024). "Additionally, a recent study reported that TCAF2 is associated with the immune microenvironment of the glioma, promoting its onset and impairing prognosis." (PMID 38019450, 2024). "In the present study, the association of TRPM8 channel-associated factor 2 (TCAF2) in glioma was investigated using bioinformatics, showing significant relationships with age, WHO grade, IDH, and 1p/19q status, as well as being an independent predictor of prognosis." (PMID 38019450, 2024). "Secondly, the mechanism underlying TCAF2 mediation of the enhancement of invasion and migration of glioma cells remains unclear, and more studies are needed to clarify the downstream mechanism of TCAF2 action in glioma." (PMID 38019450, 2024). "Raised TCAF2 levels promote glioma cell migratory/invasion properties through the epithelial-to-mesenchymal transition-like (EMT-like) process, shown by Transwell and scratch assays and western blotting." (PMID 38019450, 2024). "In the present study, the role of TCAF2 in glioma was investigated, finding that TCAF2 levels were positively correlated with significant clinicopathological features and patient prognosis." (PMID 38019450, 2024). "For further verification of TCAF2 protein levels in glioma tissues, specimens were collected at our institution, made into TMAs, and stained by IHC." (PMID 38019450, 2024). "The results of this study indicate that the overexpression of TCAF2 leads to an increase in the migratory and invasive capabilities of glioma cells, as well as a decrease in survival rates among xenograft mice." (PMID 38019450, 2024). "The results showed that upregulated TCAF2 enhanced migration/invasion properties in glioma cultures through an EMT-like process and STAT3 activation." (PMID 38019450, 2024). "Analysis of Toil-processed the TPM-format TCGA and GTEx RNA-seq data from UCSC XENA-dataset outcomes showed TCAF2 expression within glioma, GBM, and low-grade glioma (LGG) was considerably upregulated in comparison with healthy brain tissue." (PMID 38019450, 2024). "Immunohistochemistry of a glioma sample microarray showed markedly increased TCAF2 expression in glioblastoma relative to lower-grade glioma, with elevated expression predominating in the tumor center." (PMID 38019450, 2024). "Thus, it can be speculated that TCAF2 is closely associated with glioma pathogenesis." (PMID 38019450, 2024). "Overexpression of TCAF2 significantly promoted both migratory/invasive properties in glioma cells." (PMID 38019450, 2024). "However, research on TCAF2 in cancer remains limited, and its biological role and functions in glioma are not yet fully understood." (PMID 38019450, 2024). "Nevertheless, this preliminary investigation of TCAF2 in glioma has several limitations." (PMID 38019450, 2024). "In vitro and in vivo experiments demonstrated that TCAF2 promotes the malignant progression of glioma cells, proposing that TCAF2 may be a valuable target for treating glioma." (PMID 38019450, 2024). "Regression analyses showed that TCAF2 could independently predict glioma prognosis, similar to IDH status, WHO grade, and older age." (PMID 38019450, 2024). "In essence, this study investigated the role of TCAF2 in glioma." (PMID 38019450, 2024). "TCAF2 was strongly expressed within glioma and peritumoral tissue." (PMID 38019450, 2024). "Dataset outcomes revealed that TCAF2 level, age, WHO grade, IDH, and 1p/19q status were independent prognostic factors for glioma." (PMID 38019450, 2024). "It was found that neither overexpression nor knockdown of TCAF2 significantly affected glioma cell proliferation." (PMID 38019450, 2024).
glioma (continued). "Notably, STAT3 overexpression rescued the influence of TCAF2 knockdown on migration/invasion, together with EMT-like processes, suggesting that TCAF2 promotes glioma cell migratory/invasive properties through activating STAT3 signaling." (PMID 38019450, 2024). "Further probing for associations across TCAF2 levels and overall survival (OS) within TCGA data indicated that regardless of whether the diagnosis was a glioma, LGG, or GBM, cases having upregulated TCAF2 expression had shorter OS in comparison with patients having lower TCAF2 expression." (PMID 38019450, 2024).
melanoma (1 paper, 2020). A malignant, usually aggressive tumor composed of atypical, neoplastic melanocytes. "Lastly, TCAF2 is a transient receptor potential channel-associated factor involved in melanoma cell death." (PMID 32831131, 2020). "Only the module turquoise had a significant enrichment (p = 0.009) of genes whose homologs displayed prognostic value in melanoma, such as Oca2, Samhd1, Nlrc5, Irf1, Ifitm3, Sp100, Dram1, Rtn1, Tcaf2, Parp10, and Grin3a." (PMID 32831131, 2020).
metastasis (1 paper, 2023). The spread or migration of cancer cells from one part of the body (where they first appeared) to another. "Data showed that the TCAF2+ TPC ratio was associated with liver metastasis and TNM stage, but not with KRAS or BRAF mutations." (PMID 37635201, 2023). "First, we examined whether the cancer driver mutations or any other cancer markers correlated with TCAF2 expression in TPCs using the clinical data of CRC patients with or without liver metastasis." (PMID 37635201, 2023).
tumor (5 papers, 2020 to 2024). "Gain‐ and loss‐of‐function experiments validate that TCAF2 in TPCs promotes tumor cell motility, epithelial‐mesenchymal transition (EMT), and CRCLM, which is attenuated in pericyte‐conditional Tcaf2‐knockout mice." (PMID 37635201, 2023). "Pearson's correlation analysis indicated that the expression of TRPM8 was negatively correlated with the expression of TCAF2 in NG2+ TPCs of tumor xenografts." (PMID 37635201, 2023). "Taken together, our results demonstrate that the expression of TCAF2 in TPCs is regulated by high‐metastatic potential of tumor cells and the hypoxic condition." (PMID 37635201, 2023). "Next, the tandem mass tag (TMT)‐based quantitative proteomic analysis was employed to determine the mechanism by which TCAF2+ TPCs in the regulation of tumor metastasis." (PMID 37635201, 2023). "TCAF2 was positively related to tumor grade, 1p/19q, IDH status, and poor outcome." (PMID 38019450, 2024). "Nevertheless, the indirect effects of pericyte‐TCAF2 on tumor cell extravasation, seeding, and colonization may have resulted from an increased number of CTCs." (PMID 37635201, 2023). "Furthermore, we found that the TCAF2+ TPC ratio was increased in tumor tissues derived from CRC patients with liver metastasis." (PMID 37635201, 2023). "TCAF2 is highly expressed in tumor pericytes (TPCs) derived from patients with colorectal cancer liver metastasis (CRCLM), which induces the secretion of Wnt5a through inhibiting TRPM8 channel and activates the STAT3 phosphorylation in tumor cells, thus facilitating CRCLM." (PMID 37635201, 2023). "Given that TCAF2 is a binding factor for TRPM8 and can inhibit TRPM8 channel activation in tumor cells, we further evaluated whether TCAF2 exerted similar effects in TPCs." (PMID 37635201, 2023). "The co‐injected TPCs were located in the periphery of tumor vessels and played a dominant role at the endpoint, and TCAF2 in TPCs had negligible effects on MVD, vascular size, pericyte coverage, the integrity of vascular basement membrane, and tumor hypoxia in orthotopic xenografts." (PMID 37635201, 2023). "However, pericyte‐specific deletion of Tcaf2 had negligible effects on tumor microvessel density (MVD), vascular size, pericyte coverage, basement membrane integrity, vessel permeability, and tumor hypoxia." (PMID 37635201, 2023). "Collectively, these data indicate that TCAF2‐induced Wnt5a secretion through inhibiting TRPM8 in TPCs, which activates the STAT3 signaling pathway in tumor cells, thus facilitating CRCLM." (PMID 37635201, 2023). "Our results showed that deletion of TCAF2 in TPCs suppressed CRC metastasis, as indicated by the decreased number of circulating tumor cells (CTCs), and liver metastases." (PMID 37635201, 2023). "Our study revealed the pro‐metastatic effects of TCAF2 and TRPM8 in TPCs from a new perspective on ion channels, providing a potential target for inhibiting tumor metastasis." (PMID 37635201, 2023). "Immunofluorescence staining also showed that the expression of TCAF2 and Wnt5a in NG2+ TPCs was significantly increased in primary tumor tissues derived from CRC patients with liver metastasis compared with those without liver metastasis." (PMID 37635201, 2023). "TCAF2 in TPCs inhibited the expression and ion channel activity of TRPM8, promoting tumor cell EMT and metastasis via activation of the Wnt5a/STAT3 signaling pathway." (PMID 37635201, 2023). "Pericyte‐specific deletion of Tcaf2 suppressed CRC cell epithelial‐mesenchymal transition (EMT) and inhibited tumor metastasis." (PMID 37635201, 2023). "Taken together, these data indicate that TCAF2 in TPCs induces Wnt5a secretion and activates STAT3, thus promoting tumor cell EMT and facilitating CRCLM." (PMID 37635201, 2023). "Compared to the control cohort, neither overexpression nor TCAF2 knockdown considerably affected tumor growth." (PMID 38019450, 2024).
tumor (continued). "It was found that TCAF2 protein levels were markedly elevated in GBM samples compared with LGG specimens, and protein levels in samples taken from the tumor-mass center were considerably upregulated in comparison with counterpart levels within the tumor periphery." (PMID 38019450, 2024). "Since TCAF2 inhibited ion channel activity and expression of TRPM8, we further investigated whether TCAF2 induced Wnt5a expression and tumor metastasis via TRPM8." (PMID 37635201, 2023). "Exploring the binding site of TCAF2 and TRPM8 would contribute to the development of inhibitors blocking the binding of TCAF2 with TRPM8, as well as to the TPC‐targeting strategy that suppresses tumor hematogenous metastasis through hindering the interaction of TCAF2 and TRPM8 in TPCs." (PMID 37635201, 2023). "Mechanistically, TCAF2 inhibits the expression and activity of TRPM8, leading to Wnt5a secretion in TPCs, which facilitates EMT via the activation of the STAT3 signaling pathway in tumor cells." (PMID 37635201, 2023). "Given that Wnt5a can promote tumor cell EMT and metastasis by activating the STAT3 signaling pathway, we next investigated whether TCAF2 in TPCs enhanced CRC cell motility and EMT through the Wnt5a/STAT3 signaling pathway." (PMID 37635201, 2023). "TCAF1 and TCAF2 did not correlate with tumor stage or lymph node invasion (data not shown)." (PMID 36012311, 2022).
cancer (4 papers, 2022 to 2024). A tumor composed of atypical neoplastic, often pleomorphic cells that invade other tissues. "The results showed that TCAF1 and TCAF2 are expressed in cancer tissues and are located at the cytoplasmic and membrane levels." (PMID 36012311, 2022). "It is thus reasonable to believe that high levels of TRPM8 and TCAF2 co-expressions in PDAC correspond to cancer invasiveness and metastasis." (PMID 36012311, 2022).
TCAF2 also shares sentences with these, for which no sentence is quoted: breast carcinoma (1 paper); glioblastoma (1); low grade glioma (1); pancreas adenocarcinoma (1).